PDGFRB (platelet derived growth factor receptor beta)
Diseases named in the same sentence as PDGFRB in open-access papers (continued):
Sharing a sentence is not in itself a finding about the gene and the disease.
liver fibrosis (continued). "Sensitivity, specificity, PPV, and NPV of (PDGFRβ at a cutoff > 2.54 + FIB-4 at a cutoff > 1.17) to predict significant liver fibrosis in diabetic MAFLD patients were 100%." (PMID 40676525, 2025). "We found that the performance of PDGFRβ as a non-invasive marker to predict significant liver fibrosis in diabetic MAFLD was superior to the FIB-4 score." (PMID 40676525, 2025). "The sensitivity, specificity, PPV, and NPV of PDGFRβ to predict significant liver fibrosis (≥ F2) in diabetic MAFLD patients were 85%, 93.33%, 89.5%, and 90.3%, respectively, at a cutoff level > 2.54 (AUC = 0.905, CI = 0.810–1.0, P < 0.001)." (PMID 40676525, 2025). "PDGFRβ can be a promising biomarker to detect significant liver fibrosis in diabetic MAFLD patients." (PMID 40676525, 2025). "The aim of this study was to evaluate the productivity of serum PDGFRβ as a non-invasive biomarker of liver fibrosis in diabetic MAFLD patients." (PMID 40676525, 2025). "Mechanistically, TINAGL1 directly binds to and stabilizes the known profibrotic factor PDGF-BB, which leads to the activation of HSCs and triggers liver fibrosis through the PDGF-BB/PDGFRβ signaling pathway." (PMID 39781468, 2025). "Studies in the murine models of cardiac and liver fibrosis revealed Gucy1α1 elevation in activated Pdgfrβ-, Vim- and alpha smooth muscle actin (αSma)-expressing fibroblasts paralleling injury progression and resolution." (PMID 39184103, 2024). "The validity of PDGFRβ as a marker for active fibrosis was confirmed in human liver samples and 3 mouse models of liver fibrosis (DDC, CCl4, CDA-HFD) through immunohistochemistry and RT-PCR." (PMID 38888612, 2024). "The anti-PDGFRβ Fibrobody® SP02SP26-ABD shows selective and high-degree targeting of activated myofibroblasts in liver fibrosis, and qualifies as a vector for diagnostic and therapeutic purposes." (PMID 38888612, 2024). "In liver fibrosis induced by bile duct ligation, the majority of Thy 1.2 positive cells in the periportal area were also labelled by PDGFRβ-P2A-CreER." (PMID 37147343, 2023). "Whereas transgenic expression of PDGFB in the liver under albumin promoter increased collagen deposition and promoted CCl4-induced liver fibrosis, ablation of PDGFRβ in HSCs attenuated liver fibrosis." (PMID 37860002, 2023). "This strongly suggests that the PET tracer [18F]TZ-Z09591 specifically visualizes PDGFRβ expression, and thus aHSCs responsible for fibrogenesis, in a preclinical liver fibrosis model as well as in human tissue." (PMID 37733133, 2023). "Further prospective studies are required to evaluate the clinical utility of PET imaging of PDGFRβ expression using the [18F]TZ-Z09591 for the clinical assessment of liver fibrosis progression or regression based on these promising preliminary results." (PMID 37733133, 2023). "Both the Lrat- and the PDGFRβ promoters were shown to label HSCs in the context of liver fibrosis of different etiologies." (PMID 37147343, 2023). "This curcumin anti-hepatic fibrosis efficacy can be attributed to its inhibitory role through a direct binding to fibrosis-mediating proteins such as PDGFRB, Timp-1, TLR-9 and TGF-β." (PMID 36319750, 2022). "AuNRs-PDGFRβ formed by coupling AuNRs-PEG with anti-PDGFRβ antibody can precisely target the PDGFβ receptor on the surface of hepatic stellate cells, exerting an anti-hepatic fibrosis effect." (PMID 35882718, 2022). "Similar antifibrotic effects can also be achieved through direct administration of PDGF-BB specific neutralizing antibody (MOR8457) or soluble dominant negative PDGFRβ, as demonstrated in mice model of hepatic fibrosis." (PMID 34335301, 2021). "Previous publications have shown that other PDGFRβ-targeted drugs ameliorated liver fibrosis and HSC proliferation by reducing ECM deposition and proliferation of myofibroblast-like cells." (PMID 30783172, 2019).
liver fibrosis (continued). "The combination of the miRFIB-score with circulating PDGFRβ-levels further increased the predictive capacity for the diagnosis of significant liver fibrosis." (PMID 31470644, 2019). "Similar to the CCl4-induced fibrosis model, Med23 silencing also resulted in increasing mRNAs related to liver fibrosis, including Col1a1, Col3a1, Tgfβ1, Pdgfβ, Tgfβr1, Pdgfrβ, and Timp1." (PMID 31805036, 2019). "After 15 days of treatment, CLD-rats treated with liraglutide displayed lower expression of α-SMA and PDGFRβ, accompanied by reductions in extracellular matrix synthesis and deposition as demonstrated by diminished collagen expression and hepatic fibrosis." (PMID 28607430, 2017). "Analysis of our vesicle populations for collagen type I and platelet-derived growth factor receptor beta (PDGFRβ), showed an enhanced expression in the patient populations with early liver fibrosis, as compared to the healthy controls." (PMID 28232800, 2017). "In fact we identified increased stellate cell activation, a modest increase in PDGFRβ and ensuing hepatic fibrosis." (PMID 22761897, 2012). "In multivariate analysis, PDGFRβ was the only independent predictor of significant liver fibrosis (≥ F2) in diabetic MAFLD patients (p = 0.006) [OR (LL – UL 95% C.I) = 12.574 (2.065–76.558)] as well as in nondiabetic MAFLD patients (p = 0.001) [OR (LL – UL 95% C.I) = 3.313 (1.911–5.743)]." (PMID 40676525, 2025). "Importantly, CP-673451 partially reversed the effects of Metrnl knockdown on ECM deposition and HSC fibrosis, underscoring the role of Metrnl in regulating HSC activation through the PDGFRβ signaling pathway to mitigate liver fibrosis." (PMID 40393967, 2025). "This suggests that PDGFRβ is a reliable indicator of liver fibrosis severity." (PMID 40676525, 2025). "Using PDGFRβ as a biomarker could improve non-invasive assessment of liver fibrosis in this patient population by increasing the accuracy of prediction and minimizing the gray zone." (PMID 40676525, 2025). "In addition, blocking receptor tyrosine kinases such as Pdgfrβ by crenolanib via drinking water can improve thioacetamide-induced liver fibrosis in rats." (PMID 40358198, 2025). "Therefore, we examined the productivity of serum PDGFRβ as a non-invasive biomarker of liver fibrosis in diabetic MAFLD patients." (PMID 40676525, 2025). "This prompts further investigation into whether Metrnl can modulate PDGFB levels, a ligand for PDGFRβ that activates HSCs and contributes to liver fibrosis." (PMID 40393967, 2025). "In the liver fibrosis mouse model, PDGFRβ expression is upregulated in activated HSCs." (PMID 38469403, 2024). "When fibrosis is driven by PDGFRβ/STAT3 pathway activation — as occurs in ARPKD liver fibrosis or in murine models of lung and bone marrow fibrosis — PDGFR inhibitors exhibit antifibrotic efficacy but are less effective when the fibrosis is driven by other mechanisms." (PMID 39656528, 2024). "Importantly, PI3K-AKT and focal adhesion-related proteins, such as PDGFRβ, PIKR3R1, ITGB5, COL1A1, COL6A1, COL6A3, and LAMA5, are mainly associated with liver fibrosis." (PMID 38469403, 2024). "Hence, in this study, we investigate the potential of the radiolabeled Affibody molecule [18F]TZ-Z09591 targeting PDGFRβ to detect fibrogenesis in liver fibrosis." (PMID 37733133, 2023). "Furthermore, PDGFRβ-P2A-CreERT2 induced reporter expression remained specific for mesenchymal cells even under fibrogenic conditions in the CCl4 toxic liver fibrosis model." (PMID 37147343, 2023). "Resisting angiogenesis in hepatic fibrosis through the PDGFRB/ERK/HIF-1α and VEGFA/AKT/eNOS signaling pathways may serve as a promising therapeutic approach for treating hepatic fibrosis." (PMID 38155904, 2023). "Combined with the GO, KEGG and Western blot results, COL1A2, ITGAV, TLR2, ACE, and PDGFRB may be potential targets for PE treatment of liver fibrosis." (PMID 36313326, 2022).
liver fibrosis (continued). "Although LX-2 cell line enjoys great popularity among researchers interested in the elucidation of mechanisms underlying stellate cell biology and liver fibrosis, it expresses a-SMA, vimentin, GFAP, and PDGFRb suggesting that cell line retains key features of activated/transdifferentiated HSC." (PMID 32887613, 2020). "In the liver, by contrast, PDGFRβ defines and quantifies liver fibrosis." (PMID 30783172, 2019). "More importantly, the combination of the plasma levels of five miRNAs and PDGFRβ protein levels into the miRFIBP-score increased the predictive capacity for the diagnosis of significant liver fibrosis and outperformed clinical scores, such as Fib-4, the AST/ALT ratio, and APRI." (PMID 31470644, 2019). "Blockade of receptor PDGFRβ by nanoprobes may inhibit the exacerbation of liver fibrosis." (PMID 40051348, 2025). "Additionally, PDGFRβ could complement other non-invasive scores and imaging modalities, providing a more comprehensive assessment of liver fibrosis." (PMID 40676525, 2025). "Our data demonstrate, that PDGFRβ-P2A-CreERT2 specifically and efficiently marks over 90% of retinoid positive HSCs in healthy and fibrotic liver in mice upon tamoxifen injection, and that those cells give rise to Col1a1-expressing myofibroblasts in different models of liver fibrosis." (PMID 37147343, 2023). "While circulating soluble PDGFRβ has been recently used for the diagnosis of liver fibrosis independent of disease etiology, its diagnostic performance in HCC remains unknown." (PMID 34362181, 2021). "The inclusion of PDGFRβ into the miRFIB-score further improved the correlation with fibrosis severity (r = 0.4847), with a persistent possibility to differentiate patients with specific stage F2 liver fibrosis from patients with stage F0–1 fibrosis (p < 0.0001)." (PMID 31470644, 2019). "Thus it is surprising that mice which systemically express a hyperactive PDGFRβ allele do not develop more liver fibrosis than WT mice after 4 weeks of CCl4 injections." (PMID 24667490, 2014). "Factors predicting significant liver fibrosis in the diabetic MAFLD group were PDGFRβ, smoking, visceral fat, and FIB-4 score, while PDGFRβ was the only independent predictor." (PMID 40676525, 2025). "The combination of PDGFRβ at a cutoff > 2.54 and FIB-4 at a cutoff > 1.17 resulted in 100% sensitivity, specificity, PPV, and NPV for predicting significant liver fibrosis in diabetic MAFLD patients." (PMID 40676525, 2025). "The increased tracer binding was localized to the hepatic sinusoids, which were recognized by immunostaining for PDGFRβ and SIR in animals with induced liver fibrosis." (PMID 41389114, 2025). "The sensitivity, specificity, PPV, and NPV of PDGFRβ + FIB-4 in diabetic MAFLD were all 100%, indicating that adding PDGFRβ to the FIB-4 score enhanced its ability to identify severe liver fibrosis in these subjects." (PMID 40676525, 2025). "The sensitivity, specificity, PPV, and NPV of PDGFRβ at a cutoff > 2.54 and FIB-4 at a cutoff > 1.07 to predict significant liver fibrosis (≥ F2) were all 100% in diabetic MAFLD (AUC = 1, CI = 1–1, P < 0.001)." (PMID 40676525, 2025). "In all three liver fibrosis models, PET-CT imaging and biodistribution analysis of [89Zr]Zr-SP02SP26-ABD revealed increased PDGFRβ-specific uptake in fibrotic livers." (PMID 38888612, 2024). "In previous studies using murine models, the combined use of BCAAs attenuated liver fibrosis through inhibition of the TGF-β1 signaling pathway by downregulating several key pathway components, including SMAD-4, P-SMAD3L, TIMP-1, PDGFRβ, p-ERK, and COL1A2." (PMID 39495311, 2024). "During the course of our studies, two studies were published on the use of small molecular 18F- and 68Ga-labeled anti-PDGFRβ Affibody constructs (∼ 6.5 and 15 kDa) for PET imaging of liver fibrosis." (PMID 38888612, 2024).
liver fibrosis (continued). "In conclusion, we demonstrated the significance of PDGFRβ signaling across various aspects of MASH progression, including inflammation, steatosis, and liver fibrosis to tumor formation and proliferation." (PMID 39394459, 2024). "To quantify the amount of PDGFRβ-P2A-CreERT2-derived myofibroblasts, we used the triple transgenic PDGFRβ-P2A-CreERT2 x tdTomato x Col1a1-GFP mouse and induced liver fibrosis by CCl4." (PMID 37147343, 2023). "Ten DEGs including PDGFra, PDGFrb, PDGFb, PDGFd, COL1A1, COL1A2, COL5A2, ITGA5, THBS1 and IL1R1, closely related to liver fibrosis, were chosen for the real-time qRT-PCR analysis." (PMID 26691002, 2015). "HQD down-regulated the expressions of PDGFra, PDGFrb, PDGFb, PDGFd, COL1A1, COL1A2, COL5A2 and THBS1, and TGF-β and PDGF signaling pathways in the DMN-induced liver fibrosis in rats." (PMID 26691002, 2015). "PDGFRβ-targeted positron emission tomography (PET) has a great potential as an imaging biomarker for assessing disease progression and treatment responses in multiple liver fibrosis etiologies, including viral hepatitis (HBV, HCV)." (PMID 40676525, 2025). "Decreasing PDGFRβ in HSCs can reduce liver ECM deposition and alleviate liver fibrosis." (PMID 40393967, 2025). "PDGFRβ can also be useful in treatment monitoring of MAFLD patients since it is overexpressed during liver injury and its circulating levels can reveal information about the degree of liver fibrosis." (PMID 40676525, 2025). "Administration of the antihypertensive agent hydralazine to SHRs significantly ameliorated HFC-induced liver fibrosis; it suppressed the aggregation of CD68-positive macrophages and the upregulation of platelet-derived growth factor receptor beta, and collagen, type 1, alpha-1 chain." (PMID 33315911, 2020). "PDGFRs are thought to play a central role in activating HSCs and promoting liver fibrosis and cirrhosis; whether PDGFRα and PDGFRβ play independent roles in fibrogenesis is not known." (PMID 24667490, 2014).
eosinophilia (59 papers, 2009 to 2026). "Myeloid (and lymphoid) neoplasms with eosinophilia are associated with rearrangement of the tyrosine kinase (TK) genes, namely PDGFRB, PDGFRA, FGFR1, JAK2, FLT3, and ABL1 (excluding BCR-ABL1)." (PMID 39156600, 2024). "Platelet-derived growth factor receptor B (PDGFRB) gene rearrangements define a unique subgroup of myeloid and lymphoid neoplasms frequently associated with eosinophilia and characterized by high sensitivity to tyrosine kinase inhibition." (PMID 34859285, 2022). "Myeloid neoplasms with prominent eosinophilia often have rearrangements in the platelet-derived growth factor receptor α (PDGFRA) or β (PDGFRB) or are associated with core-binding factor AML." (PMID 34285820, 2021). "Activating mutations in PDGFRB have been associated with other human diseases, including Kosaki overgrowth syndrome, infantile myofibromatosis, fusiform aneurysms, acute lymphoblastic leukaemia and myeloproliferative neoplasms associated with eosinophilia." (PMID 35689379, 2022). "In the 2008 WHO classification it was recommended that cases of CMML with eosinophilia should be investigated for a PDGFRB gene abnormality and if detected, the case should be classified as a myeloid neoplasm with eosinophilia associated with PDGFRB rearrangement." (PMID 31321531, 2019). "Both the World Health Organization (WHO) and the International Consensus Classification (ICC) have updated the former category of “Myeloid/Lymphoid Neoplasms Associated with Eosinophilia and Rearrangement of PDGFRA, PDGFRB, FGFR1, or PCM1::JAK2”." (PMID 41530508, 2026). "Myeloid/lymphoid neoplasms with eosinophilia and PDGFRB rearrangements typically present as chronic myeloid neoplasms and are classified as a distinct entity in the World Health Organization (WHO) classification." (PMID 41278291, 2025). "Our patient had severe eosinophilia, thrombocytopenia, and thrombosis so we evaluated him for underlying primary HES by sending the FIP1L1–PDGFRA fusion gene, PDGFRB JAK2V617F mutation, CALR, and BCR‐ABL mutation." (PMID 35242558, 2022). "For patients with myeloid neoplasms and eosinophilia expressing PDGFRβ fusions, the recommended starting dose is 400 mg, being lowered to 100 mg during maintenance." (PMID 33418988, 2021). "Myeloid neoplasms with platelet-derived growth factor receptor β (PDGFRB) rearrangement usually present with eosinophilia in the peripheral blood and bone marrow." (PMID 33663081, 2021). "Myeloid tumors with PDGFRB rearrangement are usually characterized by eosinophilia in the peripheral blood and bone marrow." (PMID 33663081, 2021). "Among the alterations found in primary Eosinophilia, gene fusions involving PDGFRα, PDGFRβ, FGFR1 or JAK2 represent the biomarkers of WHO-defined "myeloid and lymphoid neoplasms with eosinophilia"." (PMID 34772467, 2021). "It consists of a distinct disease from myeloid/lymphoid neoplasms associated with eosinophilia and rearrangement of PDGFRA, PDGFRB, or FGFR1, or with PCM1-JAK2." (PMID 34441019, 2021). "A distinct classification of myeloid and lymphoid neoplasms associated with eosinophilia and rearrangements of PDGFRA, PDGFRB, FGFR1 or with a PCM1-JAK2 rearrangement is described in the WHO 2017." (PMID 30696948, 2019). "The category of myeloid/lymphoid neoplasms with eosinophilia and rearrangement of PDGFRA, PDGFRB, FGFR1 and PCM1-JAK2 represents an uncommon cause of eosinophilic lung infiltrate." (PMID 31744552, 2019). "For this reason, the 2008 WHO Classification of hematopietic and lymphoid tumors has introduced a separate diagnostic category for such disorders, referred to as “Myeloid and Lymphoid Neoplasms with Eosinophilia and Abnormalities of PDGFRα, PDGFRβ or FGFR1”." (PMID 26943776, 2016). "As the spectrum of malignancies associated with this rearrangement expanded, the 2008 WHO classification developed a category for these neoplasms, “Myeloid and lymphoid neoplasms associated with eosinophilia and abnormalities of PDGFRA, PDGFRB, or FGFR1 ”." (PMID 26457233, 2015).